TNF (tumor necrosis factor)
Diseases named in the same sentence as TNF in open-access papers (continued):
Sharing a sentence is not in itself a finding about the gene and the disease.
infection (continued). "IL-1β and TNF-α are typical proinflammatory cytokines that are induced at the early stage of pathogen infection to enhance macrophage survival and the bactericidal activity of leukocytes by increasing ROS production during phagocytosis." (PMID 34946096, 2021). "The expression levels of IFN-α at 7 dpi and IL-1β and TNF-α at 5 dpi were also significantly higher (P < 0.05) in the IBV+H9N2 group than in the single-infection IBV and H9N2 groups." (PMID 35211536, 2021). "Some studies in mice implicate Tumor Necrosis Factor (TNF) produced in response to the infection whereas others fail to find a role for it." (PMID 33465071, 2021). "The results showed that the mRNA levels of TNF-α and IL-1β reached the peak at 24 h after infection with mutants of RmlA; also, the survival of the mutants in macrophage was sharply decreased compared with that of the WT." (PMID 33868202, 2021). "On the other hand, C. pseudodiphtheriticum 090104 was shown to inhibit secondary infection of S. pneumoniae in vivo probably by inducing elevated TNF-alpha and interferon gamma levels." (PMID 34529731, 2021). "The activation of these signal pathways leads to the secretion of cytokines such as TNF-α and IL-1β, followed by the recruitment of more inflammatory cytokines to the infection sites by chemokines." (PMID 35069594, 2021). "Infection of human monocytes with K. kingae performed at MOIs of 1 and 10 elicited the secretion of IL-6, TNF-α, and IL-1β at 24 h post-infection in an inoculum-dependent manner." (PMID 34925328, 2021). "Immunopathology attributable to excessive TNFα has been observed in a number of infections as well as inflammatory disorders." (PMID 33680987, 2021). "In our study the phosphorylation of NF-ĸBp65 enhanced expression of IL-6, TNF-α and IL-1β, 24 h post-infection." (PMID 34233673, 2021). "Neutrophils produce TNF-α, the key cytokine involved in the initiation of immune response to M. tb and in the long-term control of infection." (PMID 35095865, 2021). "Administration of the inhibitor significantly prolonged survival of the animals and reduced the levels of circulating IL-1β and TNF-α and partly IL-6 at 20 hours after infection." (PMID 34236052, 2021). "When infection, injury, or inflammation increases in severity, polarization initially adopts the M1 conformation, leading to a systemic influx of TNF-α, IL1β, IL-12, and IL-23 to reconcile homeostasis." (PMID 34831416, 2021). "In contrast to T. marneffei yeasts, only minimal levels of IL-1β was detected in PBMCs co-cultured with conidia at 5 days post infection, whereas TNF-α production began to increase steadily after 2 days of incubation." (PMID 34912336, 2021). "Despite the differences in the magnitude of induction between each HBEC donor, combined, we observed a consistent trend of proinflammatory cytokine and chemokine (CCL2, CCL20, CXCL6, IL-6 and TNFα) inductions within 24 h post-infection with SARS-CoV-2." (PMID 34452468, 2021). "Leukocytes fight infection and regulate immunity by secreting key immunomodulatory cytokines such as interleukin-1β (IL-1β), IL-6, IL-4, and tumor necrosis factor-α to promote tissue healing." (PMID 33846295, 2021). "The upregulation of TNFα, IL6, IL1β, and IFNγ was reported as inflammatory cytokines associated with the postviral infection, which played a role in the recruitment of more immune cells for defense against the virus." (PMID 34074129, 2021). "TNF-α is a multidirectional cytokine that, in addition to its role in infection and immunity, can induce apoptosis in multiple cell types." (PMID 34369557, 2021). "Mtb-infection induced cytokine and chemokine production in M1 and M2 and tended to induce tumor necrosis factor (TNF)-α, macrophage inflammatory protein (MIP)-1α,MIP-1β and IP-10 and fractalkine in M1 and M2 (n=8)." (PMID 34899683, 2021). "On day eight post-infection, tamoxifen increased IL-2, IL-4, TNF-α and IFN-γ compared to the same group on day four." (PMID 34204678, 2021).
infection (continued). "TNF-α is the main trigger of inflammation (pain, redness, swelling, and increased temperature at the site of infection)." (PMID 34205208, 2021). "We found that in vivo Mφs isolated from DIO mice following MHV-A59 infection demonstrated decreased H3K9me3 at NFkB binding sites on the promoter(s) IL-1β, TNFα, and IL-6 compared to infected ND Mφs." (PMID 34479991, 2021). "This led to a faster and stronger local CD4 T cell response post infection, consisting of multifunctional IFNγ/TNFα-producing Th1 T cells and IFNγ/TNFα/IL-17-producing Th17 T cells, and a faster recruitment of innate immune cells." (PMID 34925371, 2021). "When comparison was made between different serotypes and primary/secondary infection, significant difference was observed in cytokines IL-1β, IL-2, IL-6, IL-8, IL-12, TNFα, IFNγ, GM-CSF, and IP-10." (PMID 34447698, 2021). "Our previous work has shown that monocytes from CL patients express ex vivo and after infection with L.braziliensis more TLR2 and TLR4 than monocytes obtained from healthy individuals; again, this was linked to TNF expression." (PMID 34691019, 2021). "In another study, children exposed to biologics (including anti-TNFα and ustekinumab) during breastfeeding in the first year of life showed average developmental milestones and infection rates similar to controls." (PMID 34122062, 2021). "The production of CXCL1, IL-1β, TNF, and IL-6 was decreased in the lungs of Trem1−/- mice at early stages on the infection (2 dpi)." (PMID 33525982, 2021). "A cytometric bead array (CBA) was used to simultaneously determine the level of cytokines IL-6, IL-10, MCP-1, IFN-γ, TNF-α, and IL-12p70 in the serum of uninfected mice and mice infected with T. gondii at six-days post-infection." (PMID 34578186, 2021). "Other molecules such as tumor necrosis factor (TNF), NO and type I IFN have also been associated with BM alterations during infection." (PMID 34987496, 2021). "Upon infection, the immune system triggers the release of immune mediators including pro-inflammatory cytokines such as tumor necrosis factor-alpha (Tnfa), interleukin-1 (Il-1), interleukin-6 (Il-6), and the type I interferons (Ifn-a/b)." (PMID 34768822, 2021). "Overall, the mRNA levels of inflammatory cytokines (TNFα, IL-6, and IL-10) were slightly elevated compared with what is seen in the lungs of deer mice (~2–5-fold increase) following experimental infection with SNV39." (PMID 34127676, 2021). "In response to this infection, immune cells produce some proinflammatory cytokines such as interleukin (IL)-1, IL-6, and tumor necrosis factor (TNF)-α; affecting homeostasis." (PMID 34221279, 2021). "TNF levels in whole lung homogenates of LysM-cre × Hif1αfl/fl mice were higher than those in control mice at 12 hours after infection." (PMID 34393650, 2021). "Infection with V. montpellierensis induced significant elevation of sFasL (P = 0.0250) and IL-1α (P = 0.0137), IL-1RA (P = 0.0095), TNF-α (P < 0.0001), IL-1β (P = 0.0470)." (PMID 34230496, 2021). "On the other hand, moDC TLR8 signaling leads to an increase in the secretion of C-C motif ligand 2 (CCL2), CCL3, CCL4, CCL5, MCP-1, TNFα, IL-8 and IL-12p40, some of which are yet to be characterized in in vitro infections of moDC." (PMID 33498725, 2021). "Comparing to wide-type ZYAH72 infection group, the mRNA levels of pro-inflammatory cytokine tumor necrosis factor-α (TNF-α) and interleukin-1β (IL-1β) in the kidney and spleen of AHFGDS infection group were significantly reduced." (PMID 34063680, 2021). "In vitro, infected macrophages produce TNF, and the amount is related to bacterial virulence and infection doses." (PMID 34067256, 2021). "The TNFα content of the ΔhtpG infection group was significantly lower than that of the WT infection and CΔhtpG infection groups (p < 0.01)." (PMID 34869065, 2021).
infection (continued). "Th1 effector cells, through the creation of interferon-gamma (IFN-γ), as a critical cytokine, along with tumor necrosis factor (TNF)-α and -β mediate protection against H. pylori, has contributed to the infection." (PMID 35083009, 2021). "By rapid killing of infected cells, TNF protects bystander cells from infection at the acceptable cost of a slightly enhanced bystander death rate." (PMID 34016976, 2021). "The levels of pro-inflammatory cytokines (TNF-α, IL-1β, IL-6, and IL-8) were markedly higher after infection than those in the normal control group." (PMID 33670217, 2021). "An apparent increase in cytokine expression including IFNs, TGFβ, and TNFα, was further observed in all groups after challenge infection." (PMID 33499363, 2021). "PAR1ΔCF mice exhibited significantly increased CVB3 genome levels, TNF-α mRNA and IL-6 mRNA expression in their hearts 8 days after infection compared with controls." (PMID 34253819, 2021). "Cytokines, such as TNF-α and IL-6, are produced by the immune system following infection and are necessary for tissue repair." (PMID 34071911, 2021). "The secreted hydrolase Hip1 has been shown to blunt the secretion of cytokines, including TNF, following infection." (PMID 34755600, 2021). "The classically activated M1 macrophages secrete proinflammatory cytokines, such as IL-1β, IL-6, IL-12, IL-23, and TNF-α, in response to stress and infection." (PMID 34360840, 2021). "The use of knock-out strains for example, shed specific light on the role of various cytokines, particularly TNFα, IFNγ, and IL-10, in the control of parasitaemia and in the induction of pathological conditions during infection." (PMID 34114560, 2021). "Interestingly, porcine reproductive and respiratory syndrome virus (PRRSV) infection leads to TNF secretion that in turn inhibits the proliferation of a subsequent CSFV C-strain infection, which may explain CSFV vaccination failures caused by PRRSV infection in the field." (PMID 34696447, 2021). "Infection triggers the release of cytokines such as interleukin 1 (IL-1), tumor necrosis factor α (TNFα), and interleukin 6 (IL-6), which stimulate the hypothalamus-pituitary-adrenal (HPA) axis to increase the cortisol levels." (PMID 34283908, 2021). "Not only is TNF-α important for macrophage activation and recruitment to the site of infection, TNF-α is also critical for granuloma formation and architecture to contain M. tb." (PMID 35095865, 2021). "Induction of STM-specific IL-17A single-producing, IFN-γ/IL-17A co-producing, TNF-α/IL-17A co-producing and IFN-γ/TNF-α/IL-17A triple-producing CD4+ T cells mainly took place after infection with highest levels reached in INF animals." (PMID 34451970, 2021). "Altogether, our results provide a strong evidence that upon infection with SARS‐CoV‐2 primary human intestinal cells generate a strong NFκB/TNF‐mediated response and produce IFN." (PMID 33904651, 2021). "Although TNF-α and IL-6 are both produced in the hyper-inflammatory condition of LgyLRV1+ infection, their regulation is different as PP2 can block secretion of TNF-α without affecting IL-6 levels." (PMID 33765083, 2021). "Changes in the expression of cytokines IL-10, IL-4, IL-6, IL-1β and TNF-α were measured in BALB/c mice, the susceptible host of S. japonicum, and in M. fortis, the resistant host, before infection and on 3, 7, 10 and 14 dpi, respectively." (PMID 34689797, 2021). "The T2 protein from MYXV (M-T2) is expressed early after infection to bind rabbit TNF with high affinity and block its biological activity, while T2 from Shope fibroma virus can additionally inhibit human TNF." (PMID 34451529, 2021). "This regulation is required to limit the levels of TNF-α, IL-1β and IL-6 in the skin after infection." (PMID 34006861, 2021). "Expression of SOCS-1 during infection correlates with reduced levels of the pro-inflammatory cytokines IL-1β, TNF-α, and IL-6 as well as antimicrobial NO and reactive oxygen species (ROS)." (PMID 33690673, 2021).
infection (continued). "Using various comparative mice infection models, it became apparent that while TNFα production is required for parasitaemia control, a timely shedding of TNFα Receptor-2 (TNFR2) is necessary to limit TNFα-mediated infection-associated immunopathology." (PMID 34114560, 2021). "They found that P2X7R was involved in dendritic cell infiltration to the site of infection, promoting TNF-α and IL-6 production in IECs, and promoting specific T cell responses during infection." (PMID 34987401, 2021). "The IFN-γ and TNF-a response was delayed to week 3 post infection in Mtb-specific CD4+ and CD8+T cells in the high dose group." (PMID 34484203, 2021). "Having established that Coccidioides resistance can be overcome in B6D2F1 mice through TNFα blockade, we wanted to examine if halting of treatment after infection would allow for restoration of resistance." (PMID 35174101, 2021). "Similar to TLR5 gene expression, secretion levels of IL-8 and TNF-α proteins from FICEs were increased significantly after infection with flagellins (p <0.05)." (PMID 34912344, 2021). "During the acute phase of infection, proinflammatory cytokines (TNF-α, IL-1β, and IL-8) promote the development of effector T cells to fight off the infection." (PMID 33717081, 2021). "Not only IFNγ impact the BM, other cytokines that are produced by Mφ, such as IL-6, TNF and type I IFN, have been also associated with disturbances in BM precursors after infection and/or inflammation." (PMID 34987496, 2021). "In fact, IL-10 genetically deficient mice showed higher mortality due to a change in the Th1 profile after infection by T. cruzi, with increasing levels of TNF-α and IFN-γ in cardiac tissue." (PMID 34215249, 2021). "Not only does TNFα play a role in controlling the initial infection with Coccidioides, we demonstrated a continuing role in mice with established control of infection." (PMID 35174101, 2021). "Multiple factors contribute to neutrophil recruitment from the circulation to the site of infection, including proinflammatory cytokines (such as IL-1α, IL-1β, TNF-α, and IL-6) and Cxcr2 chemokines (such as Cxcl1, Cxcl2, Cxcl5, and Cxcl8)." (PMID 34011393, 2021). "Th17 cells produce pro-inflammatory cytokines, such as IL-17 and tumour necrosis factor alpha (TNF-α), to act on fibroblasts, macrophages, and endothelial and epithelial cells to recruit granulocytes (especially neutrophils) to the site of infection." (PMID 33546104, 2021). "Cruz Hernandez and colleagues (2016) observed significantly higher IL-6 and TNFα expression in DENV-2 than DENV-1 in primary infection; our observation is similar, where IL-6 and TNFα were significantly elevated in DENV-2." (PMID 34447698, 2021). "Infection with S. Typhimurium alone (LT2 group) significantly induced TNF-α in all parts of the intestine and in the colon of the BB12 + LT2 piglet group." (PMID 33670419, 2021). "An increase of TNFα, along with other pro-inflammatory cytokines, was detected in the brain, blood, and kidney of S. suis-infected mice, as well as in a porcine in vivo infection model, which investigated the brain, mononuclear cells, and lung." (PMID 33763387, 2021). "The release of pro-inflammatory cytokines, classically IL-1, IL-6, and TNFα, to combat infection has a profound secondary effect on the overall physiologic system that can result in hypotension and tissue damage, as is seen in sepsis." (PMID 33504894, 2021). "For example, infection with a highly pathogenic influenza virus elevates levels of IFN-γ, IL-1, IL-6, and TNFα in patients." (PMID 34440903, 2021). "In this case, the blockade of TNF, IL-6 or IL-10R with monoclonal antibodies reduced the lung pathology and restored the resistance to infection (60 to 100% survival)." (PMID 34451529, 2021). "TRIF-/- Hoxb8 neutrophils secreted significantly more RANTES, TNF and IL-6 than WT cells upon infection." (PMID 33747981, 2021).
infection (continued). "When coinfected with IAV, the production of TNF-α was greatly suppressed in TRPV4 KO mice compared with the mono-infection model." (PMID 34804016, 2021). "Infection during pregnancy activates the mother’s immune system to release proinflammatory cytokines, such as IL-6, TNF-α, and others." (PMID 34768946, 2021). "Increased bacterial replication upon anti-TNF treatment has previously been observed in other infection models." (PMID 34093562, 2021). "Of note, we observed that the treatment with TNFα neutralizing antibody resulted in enhanced infection rates and parasite load when contrasted to the PMN- infected DC cultures not treated with such antibody." (PMID 34790196, 2021). "The results illustrated that infection with the S. choleraesuis significantly upregulated the mRNA levels of TNF-α and IL-6 in the colon." (PMID 35051090, 2021). "IL-6 and TNF-α play a key role in the physiological inflammatory response such as during infection, but also in several diseases where elevated levels of these cytokines are associated with a poor clinical outcome." (PMID 34564578, 2021). "Starting 42 days after infection, mice were treated with control or anti-TNFα antibody on the same q3/q4 schedule as above." (PMID 35174101, 2021). "Consistent with a chronic inflammatory state, the serum levels of pro-inflammatory cytokines such as TNFα, IFNγ, and IL-1β increased as a result of the infection in the WT and FPR2-/- mice, although the IL-1β increase in the FPR2-/- mice was not significant." (PMID 34784372, 2021). "A pronounced innate immune response to infection followed the peak of viral replication, evidenced by induction of cytokines (IL‐6, TNF), chemokines (CCL2, CCL5) and type I and III IFNs (IFNβ, IFNλ1/3) measured by RT–qPCR (and EV2D–F)." (PMID 34101213, 2021). "IL-33 drives ILC-cell-dependent recruitment of CCR2+ inflammatory monocytes, which resemble the TipDCs (TNF and iNOS-producing dendritic cells) previously shown to be important for control of infection." (PMID 33929319, 2021). "Infections with Rift Valley Fever virus (RVFV) clone 13 (for IFN-α) or stimulation with LPS/IFN-γ (for TNF-α and IL-6) were performed as positive controls." (PMID 34122407, 2021). "Among these molecules, TNF, which is also involved in the control of infection, plays an important role in tissue damage in the context of human disease caused by L. braziliensis." (PMID 34691019, 2021). "IFN-γ and TNF-α production stimulates macrophage functions and controls tachyzoite replication during acute and chronic phases of infection." (PMID 34578186, 2021). "The cell culture supernatants were collected 24h post-infection to determine the levels of IL-1β and TNF-α exclusively in response to the intracellular bacteria." (PMID 34690967, 2021). "When infection, injury, or inflammation increases in severity, polarization initially adopts the M1 conformation, leading to a systemic influx of TNF-α, IL1β, IL-12, and IL-23 to reconcile a homeostatic state." (PMID 34831416, 2021). "On the other hand, murine intradermal infection with the herpes simplex virus (HSV)-2 induced the synthesis of IL-33 by keratinocytes, that in turn activated the synthesis of TNF-α and IL-6 by MCs, key cytokines in reducing the severity of the infection." (PMID 34211473, 2021). "GTP vaccine strains infection alone can enhanced the mRNA expression of IL-1β, TNF-α, IL-6, IL-10, while the expression of IFN-α mRNA is inhibited." (PMID 33827620, 2021). "This inhibitory action is later counteracted by the accumulation of circulating IL-6 and TNF-α which upregulate IL-10 production, hence explaining the rise of a second peak in IL-10 when the infection occurs at CT12." (PMID 33788832, 2021). "Contrary to the mono-infection model, the level of TNF-α in the sera of TRPV4 KO mice was very low in the coinfection model." (PMID 34804016, 2021).